SIK1 (salt inducible kinase 1)
Description:
Serine/threonine-protein kinase involved in various processes such as cell cycle regulation, gluconeogenesis and lipogenesis regulation, muscle growth and differentiation and tumor suppression. Phosphorylates HDAC4, HDAC5, PPME1, SREBF1, CRTC1/TORC1. Inhibits CREB activity by phosphorylating and inhibiting activity of TORCs, the CREB-specific coactivators, like CRTC2/TORC2 and CRTC3/TORC3 in response to cAMP signaling. Part of a sodium-sensing signaling network, probably by mediating phosphorylation of PPME1: following increases in intracellular sodium, SIK1 is activated by CaMK1 and phosphorylates PPME1 subunit of protein phosphatase 2A (PP2A), leading to dephosphorylation of sodium/potassium-transporting ATPase ATP1A1 and subsequent increase activity of ATP1A1. Acts as a regulator of muscle cells by phosphorylating and inhibiting class II histone deacetylases HDAC4 and HDAC5, leading to promote expression of MEF2 target genes in myocytes. Also required during cardiomyogenesis by regulating the exit of cardiomyoblasts from the cell cycle via down-regulation of CDKN1C/p57Kip2. Acts as a regulator of hepatic gluconeogenesis by phosphorylating and repressing the CREB-specific coactivators CRTC1/TORC1 and CRTC2/TORC2, leading to inhibit CREB activity. Also regulates hepatic lipogenesis by phosphorylating and inhibiting SREBF1. In concert with CRTC1/TORC1, regulates the light-induced entrainment of the circadian clock by attenuating PER1 induction; represses CREB-mediated transcription of PER1 by phosphorylating and deactivating CRTC1/TORC1 (By similarity).
Synonyms: SIK-1; SIK; SNF1LK; msk; DEE30; SIK1B
Tractability: Small molecule: a high-quality ligand is known; it belongs to a druggable protein family. PROTAC: ubiquitination databases record sites on it; a small molecule that binds it is known.
Target class: CAMK protein kinase group; CAMK protein kinase CAMK1 family; Protein Kinase; Kinase; Enzyme; CAMK protein kinase QIK subfamily
Chemical probes: HG-9-91-01 (high quality), JRD-SIK1/2i-4 (high quality), MRIA9 (high quality), YKL-05-099
Gene: Protein-coding gene on chromosome 21 (43,414,483 to 43,427,131, reverse strand). Ensembl gene ENSG00000142178.
Subcellular location: Cytoplasm; Nucleus
Subcellular location (Human Protein Atlas): Nucleoplasm; Vesicles
Pathways (Reactome):
Circadian clock: Phosphorylated BMAL1:CLOCK (ARNTL:CLOCK) activates expression of core clock genes
Gene Ontology:
Molecular function: 14-3-3 protein binding; ATP binding; magnesium ion binding; protein binding; protein kinase binding; protein serine kinase activity; protein serine/threonine kinase activity; cAMP response element binding protein binding; histone deacetylase binding; protein kinase activity
Biological process: intracellular signal transduction; positive regulation of anoikis; protein autophosphorylation; protein phosphorylation; cardiac muscle cell differentiation; entrainment of circadian clock by photoperiod; negative regulation of gluconeogenesis; negative regulation of triglyceride biosynthetic process; regulation of cell differentiation; regulation of mitotic cell cycle; regulation of myotube differentiation; regulation of sodium ion transport; anoikis; negative regulation of transcription by RNA polymerase II
Cellular component: cytoplasm; nucleus
Gene-disease validity (ClinGen):
ClinGen rates the evidence that SIK1 causes each of these diseases.
genetic developmental and epileptic encephalopathy (autosomal dominant): Limited. A complex neurodevelopmental disorder characterized by a range of developmental delays and epileptic encephalopathy phenotypes.
Homologues: Orthologues: chimpanzee SIK1 (99% identical), macaque SIK1 (97% identical), rat Sik1 (81% identical), mouse Sik1 (81% identical), guinea pig SIK1 (81% identical), pig SIK1 (80% identical), dog SIK1 (77% identical), zebrafish sik1 (60% identical), Drosophila melanogaster Nuak (32% identical), Caenorhabditis elegans ZK524.4 (20% identical), Drosophila melanogaster Snrk (20% identical), Caenorhabditis elegans C27D6.11 (13% identical), and 2 more. Paralogues in human: SIK2 (48% identical), SIK3 (38% identical), BRSK2 (25% identical), BRSK1 (25% identical), SNRK (23% identical), NUAK1 (23% identical), NUAK2 (22% identical), PRKAA1 (22% identical), PRKAA2 (21% identical), HUNK (20% identical), MELK (20% identical), NIM1K (17% identical), and 5 more.
Diseases named in the same sentence as SIK1 in open-access papers:
SIK1 is named in the same sentence as 96 diseases in open-access papers, as found by Europe PMC text mining. Sharing a sentence is not in itself a finding about the gene and the disease. The quoted sentences say what the papers report.
breast carcinoma (22 papers, 2014 to 2025). "In orthotopic breast cancer models, reduced expression of the gene encoding SIK1 is closely associated with the development of distant breast cancer metastasis." (PMID 39063214, 2024). "Taken together, these results indicate that the loss of SIK1 participate in promoting breast cancer cell invasiveness through the induction of SCN5A expression and NaV1.5 activity." (PMID 31819138, 2019). "In breast cancer, a reduced expression of SIK1 has been associated with metastatic progression and with a poor outcome." (PMID 31819138, 2019). "A reduced expression of SIK1 has been identified in breast cancer and has been associated with metastatic progression and with a poor outcome." (PMID 31819138, 2019). "Clinical studies have shown that reduced levels of SIK1 are associated with distal metastases and poor outcome in breast cancer, and SIK1 expression has been associated with a tumour suppressor function." (PMID 25384047, 2014). "Furthermore, reduced expression of SIK1 is associated with the faster appearance of distal metastasis, that is cancer spreading to distal organs or lymph nodes, and poor prognosis in human breast cancer." (PMID 36731029, 2023). "SIK1 has shown to stimulate the oxidative phosphorylation, which will result in the inhibition of breast cancer cell proliferation via inhibiting the glycolysis." (PMID 36268271, 2022). "In the current study, we confirmed a reduction of SIK1 expression in breast tumours, and further identified that reducing SIK1 expression in breast cancer cells induced SCN5A expression and NaV1.5-dependent invasiveness." (PMID 31819138, 2019). "Reduced SIK1 expression is correlated with poor prognosis in two large human breast cancer data sets." (PMID 29296210, 2017). "SIK1 acts as a tumour suppressor and is downregulated in many cancers including breast cancer." (PMID 36183245, 2023). "Knock‐down of SIK1 increases VGSC‐induced invasiveness in breast cancer cells." (PMID 36183245, 2023). "Hence, it is that low expression levels of SIK1 in breast cancer cells induce the activity and expression of Nav1.5, followed by high expression of SNAI1, triggering the EMT and metastasis observed in breast cancer cells." (PMID 32792949, 2020). "Among the significantly different expressed genes, we found the 3’-UTR of SIK1 contained potential binding sites for miR-183-5p according to the miRWalk database, and it was a pivotal result for us as SIK1 has been documented to inhibit tumor progression in both thyroid and breast cancer." (PMID 40115013, 2025). "Indeed, SIK1 is downregulated in many cancers including breast cancer, supporting this possibility." (PMID 36183245, 2023). "Nav1.5 overexpression increases metastasis and invasiveness of breast cancer cells by altering H+ efflux and promoting epithelial-to-mesenchymal transition and the expression of cysteine cathepsin, possibly due to reduced expression of salt-inducible kinase 1 (SIK1)." (PMID 34722688, 2021). "Salt-inducible kinase 1 (SIK1) is an LKB1-dependent kinase that inversely correlates with poor prognosis and distal metastases in breast cancer." (PMID 36230714, 2022).
breast carcinoma (continued). "By intersecting RNA-seq data and bioinformatic prediction results, we focused on SIK1, a protein of AMP-activated kinase (AMPK) family, which has been suggested as a tumor suppressor in many solid tumors, such as HCC, breast cancer, colorectal cancer." (PMID 35780119, 2022). "In all breast cancer combined, high expression of LKB1, AMPK, LYK5, MARK1, MARK2, NUAK2, PAK1 (both probe sets), SIK1, SIK2, BRSK1, BRSK2, SNRK, and QSK was positively correlated with improved survival compared to low expression of these genes." (PMID 34084284, 2021). "In addition to NHE-1, salt-inducible kinase-1 (SIK-1) also plays a prominent role in regulating Nav1.5-dependent epithelial-mesenchymal transition (EMT) and invasiveness in highly aggressive human breast cancer cell lines such as MDA-MB-231." (PMID 35204811, 2022).
ovarian carcinoma (11 papers, 2017 to 2026). A malignant neoplasm originating from the surface ovarian epithelium. "It has been reported in the literature that reduced SIK1 expression is associated with poor prognosis in ovarian cancer patients." (PMID 37670972, 2023). "A recent study observed that miR-141 can endorse the multiplication of ovarian cancer cells by inhibiting SIK1." (PMID 34887922, 2021). "SIK-1, -2, and -3 have been demonstrated to be acting as tumor suppressors and also tumor promoters; the latest example being of SIK2 which was shown to be acting as a metastasis promoter in ovarian cancer." (PMID 31798532, 2019).
lung cancer (9 papers, 2016 to 2024). A malignant neoplasm involving the lung. "Sik1-lnc is another lncRNA adjacent to salt-inducible kinase 1 (SIK1) and can be abnormally expressed in lung cancer." (PMID 36817434, 2023). "Knock-out of SIK1 and SIK3 increased tumor growth in a mouse model of oncogenic KRAS-driven lung cancer." (PMID 39544365, 2024). "LncRNA SIK1-LNC inhibits the proliferation and metastasis of lung cancer cells, and its expression is downregulated in lung cancer." (PMID 35113786, 2022). "Moreover, SIK1-LNC considerably repressed the propagation of lung cancer cells, signifying that SIK1-LNC served as a novel biomarker and target for lung cancer therapeutic approaches.TSLC1, as a tumour suppressor gene in various cancers, is considerably repressed in NSCLC tissues and cell lines." (PMID 36817434, 2023).
epilepsy (8 papers, 2017 to 2024). A brain disorder characterized by episodes of abnormally increased neuronal discharge resulting in transient episodes of sensory or motor neurological dysfunction, or psychic dysfunction. "In the present study, we investigated the effect of the C-terminal truncated mutation of SIK1 on epilepsy by inducing seizures in SIK1-MT mice." (PMID 35887274, 2022). "Epilepsy-associated SIK1 mutant mice were subjected to NMDA- and PTZ-induced seizures, rodent models for infantile spasms, and temporal lobe epilepsy." (PMID 35887274, 2022). "Although the relevance between the SIK1 mutation and autistic behaviors has been uncovered in SIK1-MT mice, the effect of the SIK1 mutation on epilepsy remains enigmatic." (PMID 35887274, 2022). "The epilepsy-associated mutation of SIK1 canceled the pharmacological effects of the ACTH treatment on NMDA-induced seizures." (PMID 35887274, 2022). "TRIP10 encodes a cytoskeletal binding protein involved in endocytosis that suppresses glucose uptake in response to insulin signaling, GPR108 encodes an orphan G-protein-coupled receptor, and SIK1 encodes a salt-inducible kinase with roles in cancer, epilepsy, and myeloid signaling." (PMID 39302339, 2024). "Although glial cell‐induced inflammation is also involved in the development of epilepsy, the present study primarily focused on the role of SIK1 in the regulation of neuronal overactivation." (PMID 37919236, 2023). "Collectively, our data indicate that SIK1 is a critical factor involved in seizure genesis by modulating neuronal excitabilities, thereby providing a potential therapeutic target for epilepsy." (PMID 37919236, 2023). "More recent work confirms the further identification of SIK1 mutations and resulting alterations MEF2C regulation in pediatric epilepsies." (PMID 36731029, 2023). "Other disorders with relatively high rates of ASD features alongside epileptic encephalopathy include HCN1-related epilepsy (67%) and SIK1-related epilepsy (50%)." (PMID 28649286, 2017). "Targeting SIK1 through the development of selective inhibitors may lead to disease‐modifying therapies that reduce epilepsy progression." (PMID 37919236, 2023). "Exome sequencing has identified mutations in the SIK1 gene in developmental epilepsies, which is consistent with the important roles for SIK1 targets including MEF2C and CRTC1/CREB transcriptional target genes in neurodevelopment and epilepsy pathogenesis." (PMID 36731029, 2023). "As another epilepsy model, pentylenetetrazol was injected into the adult SIK1 mutant mice." (PMID 35887274, 2022). "We next examined whether SIK1 is also involved in temporal lobe epilepsy, a major type of epilepsy in adulthood." (PMID 35887274, 2022). "In this study, we used the recently developed inhibitor YKL‐06‐061, which has a high affinity for SIK1 and 3, but to a lesser extent for SIK2, and tested its effects on seizure development in rodent epilepsy models." (PMID 37919236, 2023).
Hypertension (7 papers, 2012 to 2026). The presence of chronic increased pressure in the systemic arterial system. "In human genetic studies, single nucleotide polymorphisms in the SIK1 gene have been associated with hypertension." (PMID 41543628, 2026). "SIK1, as part of the sodium-sensing network, is likely to have a part in the development of high blood pressure, which is often considered one of the many risk factors in AMD." (PMID 39546296, 2024). "In 2009, Stenström reported that blocking the salt-inducible kinase 1 network prevented the increase in cell sodium transport caused by G460W, a hypertension-linked mutation in human α-adducin." (PMID 22272309, 2012). "As NF-κB p65-driven neuroinflammation in the pathogenesis of hypertension, we next used biochemical experiments to observe the expression level of NF-κB p65 pathway in Sik1-cKO mice after an HSD." (PMID 41543628, 2026). "Our findings suggest​ that neuronal Sik1 may be involved in​ the regulation of hypothalamic neuroinflammation in hypertension via the NF-κB p65 signaling pathway." (PMID 41543628, 2026). "The NR4A2 gene has been reported to be important for cytokine regulation and may contribute to inflammation in the renal medulla in hypertension; the activation of NR4A2 in response to angiotensin II is further modulated by SIK1." (PMID 41169019, 2025). "‘Unknown I’ contained a diverse set of key driver genes such as SGK1, SIK1 and SLC10A6 (sodium metabolism and hypertension), MT2A and TSC22D3 (glucocorticoid signaling), GADD45G, ERRFI1, GPRC5A, and EGFR (cell growth and apoptosis), and CEBPB, CEBPD, and KCNA5 (heart development and function)." (PMID 25033284, 2014).
hepatocellular carcinoma (6 papers, 2017 to 2025). A malignant tumor that arises from hepatocytes. "A previous study indicates that salt-inducible kinase 1 (SIK1) can be directly bound and regulated by miR-25-3p in hepatocellular carcinoma." (PMID 36744005, 2023). "In a hepatocellular carcinoma xenograft tumor model, overexpression of SIK1 can significantly inhibit EMT, tumor growth and lung metastasis." (PMID 35346195, 2022). "SIK1 has been reported as a tumor suppressor gene in hepatocellular carcinoma by regulating β-catenin signaling." (PMID 35780119, 2022). "Several studies revealed that the expression of SIK1 is downregulated in ovarian cancer and hepatocellular carcinoma." (PMID 35346195, 2022). "Our previous study reported that down-regulation of SIK1 accelerates the growth and invasion of hepatocellular carcinoma (HCC)." (PMID 27911266, 2017). "The activation of SIK1 suppresses metastasis through the AMP-activated protein kinase (AMPK) pathway, and inhibits lipid synthesis in human hepatoma cells." (PMID 28800357, 2017).
diabetes (5 papers, 2020 to 2025). "SIK1 also participates in other processes of human diseases, especially in diabetes and tumorigenesis." (PMID 39959414, 2025). "SIK1 has multiple physiological functions such as the regulation of hepatic gluconeogenesis and lipogenesis, which is closely related to diabetes mellitus and NAFLD." (PMID 32020874, 2020). "Upregulating hepatic SIK1 by ZQR may represent an efficient strategy for treating diabetes with NAFLD." (PMID 32020874, 2020). "Therefore, identifying strategies to activate SIK1 may regulate the disorder of glycolipid metabolism in patients with diabetes with NAFLD through the SIK1/CRTC2 signaling pathway." (PMID 32020874, 2020). "Although SIKs (SIK1, SIK2, and SIK3) have shown critical roles in multiple contexts of physiology and participate in distinct human diseases, such as cancer, diabetes, colitis, and sepsis, the role of SIKs in psoriasis is poorly understood." (PMID 39959414, 2025). "Although more in vivo and clinical studies are required to further solidify our findings, the current study with in vitro experimental results still sheds new light on targeting SIK1 and the CRTC2 signaling for diabetes therapy." (PMID 33013689, 2020). "Taken together, this study suggests that enhancing SIK1 activity with ZQR would be expected to decrease hyperglycemia and hyperlipidemia as well as hepatic lipid storage in patients with diabetes with NAFLD." (PMID 32020874, 2020).